OGFR (opioid growth factor receptor)
Diseases named in the same sentence as OGFR in open-access papers (continued):
Sharing a sentence is not in itself a finding about the gene and the disease.
tumor (23 papers, 2008 to 2025). "Nevertheless, splicing defects and disrupted protein levels were also observed for multiple tumor suppressor genes, including OGFR and HIP1R (Huntingtin Interacting Protein 1-related), two factors known to suppress cell proliferation." (PMID 41290606, 2025). "MET neutralization favored cell proliferation, and silencing the opioid growth factor receptor promoted tumor cell replication." (PMID 37509632, 2023). "RHOT2 and OGFR were significantly up-regulated in the GBM3 tumours (p < 0.05 and p < 0.01, respectively)." (PMID 30208958, 2018). "Moreover, a low-dose of naltrexone upregulated the expressions of the opioid growth factor receptor and apoptotic factors (PARP, caspases 3 and 9, Bax) and downregulated the expressions of Ki67 and Bcl-2, causing apoptosis in tumor cells." (PMID 37509632, 2023). "OGF, a chemically termed [Met5]-enkephalin, is an endogenous pentapeptide with potential antineoplastic and antiangiogenic activities that binds to and activates the OGFr, present on some tumor cells and vascular cells, thereby inhibiting tumor cell proliferation and angiogenesis [29, 30•, 31]." (PMID 35648340, 2022). "As for the other opioid receptor targets, the OGFR has shown inhibitory effects in tumor growth, while the role of DOR and KOR are even more controversial with data showing both activating and suppressing effects which can be explained by a different profile of receptor expression." (PMID 35463331, 2022). "Low-dose NTX carries out an intermittent OGFr blockade and OGF-OGFr axis upregulation activation which inhibits cell replication and has been reported to play a role in reducing tumor progression, [36•] whereas higher NTX doses cause continuous OGFr blockade, which results in enhanced cell growth." (PMID 35648340, 2022). "For example, RHOT2 and OGFR were significantly up-regulated in the GBM3 tumours." (PMID 30208958, 2018). "Using a human ATC cell line, KAT-18, in a tissue culture model, and confirming the presence of OGF and OGFr in these human cells under in vitro conditions, we report for the first time that opioids do indeed function in these deadly neoplasias, subserving as modulators of cell proliferation." (PMID 19835629, 2009). "However, another type of receptor called opioid growth factor receptor (OGFr), formerly known as ζ-receptor, has important properties, its stimulation by MENK causing inhibition of tumor cell proliferation, thus opening a new chapter in the research of the antitumoral potential of enkephalins." (PMID 34068618, 2021). "OGFR gene expression was highest while MOR gene expression was lowest, with comparable values between control and tumor samples on every overall gene expression." (PMID 35359418, 2022). "We investigated the normalized gene expression of μ, κ, δ opioid receptors (MOR, KOR, DOR), Opioid Growth Factor (OGFR), and Toll-Like 4 (TLR4) receptors in normal and tumor samples from twelve solid tumor types." (PMID 35359418, 2022). "Previous work has suggested that intermittent or low-dose NTX enhances OGF-OGFr signaling via a compensatory rebound mechanism, thereby inhibiting tumor growth, whereas continuous NTX exposure may suppress the OGFr expression and promote cell growth." (PMID 41226687, 2025). "Additionally, overall survival (OS) is increased by high CB2 and OGFR tumor tissue gene expression and reduced by high delta OPRD tumor tissue gene expression." (PMID 37627066, 2023). "However, MOR, DOR, and κ opioid receptors (KOR), in addition to opioid growth factor receptor (OGFR) and Toll–like receptor 4 (TLR4), have been shown to promote tumor cell migration." (PMID 35359418, 2022).
tumor (continued). "Also, low-dose NTX was able to upregulate OGFr expression and the apoptosis-related factors Bax, caspase-9, caspase-3 and PARP and down-regulate the expression of Bcl-2 and Ki67 to promote tumor cell apoptosis." (PMID 35648340, 2022). "The MOR and OGFR expression data from TCGA database were similar to our sample size data with lower expression of MOR and higher expression of OGFR in tumoural samples with a skewed distribution for MOR expression in tumor tissue both in patients with and without recurrence." (PMID 35463331, 2022). "While we found a significantly higher MOR and OGFR expression in tumor tissue samples, we did not detect differences in expression of the receptors between subjects with and without recurrence in the matched analysis." (PMID 35463331, 2022). "The nuclear membrane receptor OGFr, which responds to the endogenous opioid peptides OGF or met-enkephalin, is a known negative regulator of cell proliferation, which controls, amongst other processes, tumour growth and angiogenesis." (PMID 35004315, 2021).
infection (1 paper, 2023). The state of being infected such as from the introduction of a foreign agent such as serum, vaccine, antigenic substance or organism. "For Atlantic salmon, OGFR might be involved in the depletion of mucous cells infection of Gyrodactylus salaris (Monogenea) via suppression of DNA synthesis and a profound decrease in basal cell proliferation." (PMID 37175446, 2023).
OGFR also shares sentences with these, for which no sentence is quoted: diabetes type 1 (2 papers); dry eye (2); type 2 diabetes (2); autoimmune disease (1); breast carcinoma (1); colon carcinoma (1); follicular thyroid cancer (1); glioma (1); Glucose intolerance (1); Hypertension (1); leiomyosarcoma (1); multiple sclerosis (1); myxoid liposarcoma (1); neuroblastoma (1); ovarian tumor (1); prostate carcinoma (1); thyroid cancer (1).